ITGA7 (integrin subunit alpha 7)
Diseases named in the same sentence as ITGA7 in open-access papers (continued):
Sharing a sentence is not in itself a finding about the gene and the disease.
Sepsis (2 papers, 2023 to 2025). Sepsis is defined as life-threatening organ dysfunction caused by a dysregulated host response to infection. "In line with Ilk1 and Fermt2, genes encoding for the integrin subunits (Itga7 and ItgB1) were upregulated (more than 2-fold; P < 0.001 versus healthy control mice) after five days of sepsis." (PMID 41385533, 2025). "Similar to the TA, gene expression of Itga7, ItgB1, Tln1, Vcl1 and Parvb was upregulated in sepsis." (PMID 41385533, 2025). "A cut-off value of -14.0 was selected for panel ADM+FAM20A+ITGA7+MPP9+OLAH for discrimination of SIRS and sepsis groups from controls, which provides a positive predictive value (PPV) and negative predictive value (NPV) each of 100%." (PMID 38332914, 2023). "In rAAV-sh-controls, sepsis induced upregulation across TA and EDL muscle of Ilk1 and Fermt2 and integrin-receptor-complex-related genes Itga7, ItgB1, Tln1, Lims1, Lims2, Parva (P < 0.001), whereas in SOL muscle Lims1, Lims2 and Fermt2 were not and Vcl1 (P < 0.001) was upregulated." (PMID 41385533, 2025).
arrhythmogenic right ventricular cardiomyopathy (1 paper, 2025). "ITGA7 is involved in eight pathways, including hypertrophic cardiomyopathy (HCM), arrhythmogenic right ventricular cardiomyopathy (ARVC), dilated cardiomyopathy (DCM), PI3K-AKT signalling, and actin cytoskeleton regulation." (PMID 41468376, 2025).
atherosclerosis (1 paper, 2025). A disease characterized by the build-up of fatty material and calcium deposition in the arterial wall resulting in partial or complete occlusion of the arterial lumen. "In atherosclerosis, ECs communicated extensively with pericyte cells and SMCs through LAMININ (LAMA5-(ITGA1+ITGB1), LAMA5-(ITGA7+ITGB1), LAMB2-(ITGA6+ITGB4), LAMB2-(ITGA6+ITGB1)) and COLLAGEN (COL4A1-(ITGA1+ITGB1), COL4A2-(ITGA1+ITGB1)) pathways." (PMID 40225569, 2025).
bladder urothelial carcinoma (1 paper, 2018). "Elevated ITGA7 expression levels were also significantly associated with poor overall survival of bladder urothelial carcinoma patients." (PMID 29721158, 2018).
clear cell renal carcinoma (1 paper, 2018). A malignant epithelial neoplasm of the kidney characterized by the presence of lipid-containing clear cells within a vascular network. "High ITGA7 expression (z score >= 2) was significantly associated with poor overall survival of clear cell renal carcinoma patients." (PMID 29721158, 2018).
diabetes (1 paper, 2013). "The five increased calcium genes (Myl6b, Casq2, Itga7, Cacnb2 and Sln) have not had changed expression in previous diabetes studies." (PMID 24199937, 2013).
dystrophin deficiency (1 paper, 2016). "Moreover, transgenic overexpression of ITGA7 reduces the skeletal-muscle pathology associated with dystrophin deficiency, and this integrin was highly up-regulated in both mutant samples (both at 1 × 107versus 1 × 106 in WT)." (PMID 27099343, 2016).
endometriosis (1 paper, 2021). The growth of functional endometrial tissue in anatomic sites outside the uterine body. "Further research is needed to elucidate the role of this new target gene in endometriosis, and ITGA7, ITGBL1, SORBS1 and IGHM may be therapeutic target genes." (PMID 34409913, 2021). "Above all, ITGA7, ITGBL1 and SORBS1 may be associated with cell proliferation, invasion and migration of endometriosis, hsa-miR-6745 may be a potential miRNA biomarker, and its high expression may be associated with poor prognosis." (PMID 34409913, 2021).
granulocytic sarcoma (1 paper, 2025). A tumor mass composed of myeloblasts, neutrophils and neutrophil precursors. "The role of ITGA7 and ECM in AML with granulocytic sarcoma (GS) cells was first reported in the study performed by Kobayashi and colleagues." (PMID 41008552, 2025).
Hypertension (1 paper, 2019). The presence of chronic increased pressure in the systemic arterial system. "In another independent replication cohort consisting of 3,183 African American samples from Hypertension Genetic Epidemiology Network (HyperGEN) and the Genetic Epidemiology Network of Arteriopathy (GENOA), the top genes achieved P-values of 0.04 (ITGA7), 0.08 (SLCO2A1), and 0.02 (POT1)." (PMID 30863429, 2019).
injury (1 paper, 2022). Damage inflicted on the body as the direct or indirect result of an external force, with or without disruption of structural continuity. "Recent data shows another type of Itga7-expressing cell in muscle fiber, referred to by the authors as Itga-7+ glial cells, which, upon muscle nerve lesion, release neurotrophins and tenascin C to contribute to NMJ repair following acute nerve injury." (PMID 36614029, 2022).
liver fibrosis (1 paper, 2025). "ITGA7, important for insulin and glucose metabolism, Taylor (2018) showed hypermethylation, as did PLXND1, a therapeutic target in liver fibrosis and associated with adipocyte lipolysis, further linking these epigenetic changes to the metabolic disruptions observed due to prenatal-BPA treatment." (PMID 40914344, 2025).
neuroblastoma (1 paper, 2026). Neuroblastoma (NB) is the most common solid, extracranial childhood tumor. "In parallel, for the in vitro mechanistic study, SH-SY5Y neuroblastoma cells treated with MPP+ and transfected with ITGA7-siRNA were utilized to examine the involvement of apoptosis-related signaling pathways." (PMID 42075542, 2026).
oral squamous cell carcinoma (1 paper, 2022). "ITGA7 acts as a pro-oncogene, promoting the stemness of oral squamous cell carcinoma cells and subsequently inducing tumourigenicity and metastasis." (PMID 36267977, 2022).
osteoporosis (1 paper, 2022). A condition of reduced bone mass, with decreased cortical thickness and a decrease in the number and size of the trabeculae of cancellous bone (but normal chemical composition), resulting in increased fracture incidence. "In the milieu of osteoporosis, Huang T and colleagues demonstrated that ITGA7 was drastically inhibited in ovariectomy (OVX) mice." (PMID 35568813, 2022). "Therefore, this study contributes a novel pathway, ATF1/miR-214-5p/ITGA7 axis, involved in the regulation of bone resorption, which might provide a new option for the treatment of human osteoporosis." (PMID 35568813, 2022).
ovarian carcinoma (1 paper, 2024). A malignant neoplasm originating from the surface ovarian epithelium. "miR-320a in small extracellular vesicles secreted by tumor cells targets integrin subunit alpha 7 in ADSCs and drives CAF-like activation, which in turn facilitates omental metastasis of ovarian cancer." (PMID 38233863, 2024).
ovarian tumors (1 paper, 2024). "In addition, intraperitoneal injection of ADSCsmiR-320a also significantly diminished ITGA7 levels in the omentum of mice orthotopically transplanted with ovarian tumors." (PMID 38233863, 2024).
pancreatic cancer (1 paper, 2021). "For example, Wei-Dong Shi identified 12 human pancreatic cancer highly metastatic cell lines, SW19 × 90HM cells, including ITGA7 through microarray analysis." (PMID 33546693, 2021). "A total of 8 immune genes (ITGA7, RBM14, DENND4B, LQK1, ZNF709, COL7A1, SP1, NCBP2) were identified as independent prognostic factors of pancreatic cancer, which were used to construct a clinical predictive model." (PMID 33546693, 2021).
progressive muscular dystrophy (1 paper, 2025). "Consistent with previously study, ITGA7 serves as a ‘bridge’ connecting muscle fibers to the ECM, and its deficiency leads to progressive muscular dystrophy." (PMID 40758665, 2025).
prostate tumors (1 paper, 2009). "Further, it was demonstrated that induced expression of ITGA7 suppresses growth of prostate tumors in mice." (PMID 19653896, 2009).
teratoma (1 paper, 2020). A non-seminomatous germ cell tumor characterized by the presence of various tissues which correspond to the different germinal layers (endoderm, mesoderm, and ectoderm). "The level of mRNAs encoding Pax3 was significantly higher, while the expression of Nfix, Eno3, Mck, Mef2a, and Itga7 was significantly lower in Pax7−/− teratomas, as compared to Pax7+/+ teratomas." (PMID 32552916, 2020). "The level of mRNAs encoding Pax3 was significantly higher, while the expression of Nfix, Eno3, Mck, Mef2a, and Itga7 was significantly lower in Pax7−/− teratomas, as compared to Pax7+/+ ones." (PMID 32552916, 2020).
tongue squamous cell carcinoma (1 paper, 2024). A squamous cell carcinoma that arises from the tongue. "Additionally, ITGA7 is expressed in tongue squamous cell carcinoma, where ITGA7+ cells exhibit higher expression of stem cell markers CD44 and CD133 compared to ITGA7-cells (Lv, Yang, and Yang, 2020)." (PMID 39239559, 2024).
uveal melanoma (1 paper, 2017). A melanoma derived from melanocytes of the uveal tract. "Promoter hypermethylation was extensively observed in the ITGA7, NDRG2 and PITX2 genes (85% methylated samples) in uveal melanoma." (PMID 28924151, 2017).
tumor (37 papers, 2006 to 2026). "Studies have shown that the downregulation or mutation of ITGA7 is associated with increased tumor aggressiveness and poor prognosis in various cancers, including LMS." (PMID 40076599, 2025). "This can be due to that ITGA7 is associated with poor pathological differentiation, large tumor size, and advanced TNM stage in NSCLC patients, which are well‐studied risk factors for prognosis." (PMID 31418948, 2019). "In contrast, treating sensitive tumor cells with temsirolimus induced a significant loss of cell surface ITGA7." (PMID 29721158, 2018). "As high frequency of ITGA7+ cells was clinically associated with tumour invasion and metastasis, the effect of ITGA7 on metastasis was further studied." (PMID 27924820, 2016). "Loss or mutation of ITGA7 may impair this apoptotic pathway, allowing cancer cells to evade programmed cell death and contributing to tumor progression." (PMID 40076599, 2025). "The interaction between ITGA7 and HtrA2 can induce apoptosis in cancer cells, suggesting a tumor-suppressive function." (PMID 40076599, 2025). "The integrin genes ITGA5 and ITGA7 showed significantly enhanced transcript counts in the GBM tissue compared to the grade III tumor sample." (PMID 41366031, 2025). "In LMS, the specific pattern of ITGA7 expression and its prognostic implications require further investigation to fully elucidate its role in tumor progression." (PMID 40076599, 2025). "For example, elevated spatial expressions of ITGA5 transcripts were detected primarily in tumor ECs, whereas ITGA7 transcripts were expressed mainly in TCs and Ast-like cells." (PMID 41366031, 2025). "Increased expression of TIMP1, MMP1, AGRN, UNC5A, and ADAMTS4 was observed, while the expression of UNC5C, TINAG, SPOCK3, and ITGA7 was reduced in the normal FHC cells compared to the HCT8 tumor cells." (PMID 39011483, 2024). "Highly metastatic tumor cells suppress ITGA7 via small extracellular vesicle delivery of miR-320a to trigger the CAF-like activation of ADSCs, thereby boosting tumor metastasis." (PMID 38233863, 2024). "Consistent with in vitro results, circ_ITGA7 overexpression reduced tumor volume and weight; moreover, circ_ITGA7 overexpression combined with irradiation led to a synergistic inhibition on tumor growth." (PMID 36694626, 2023). "In this analysis, it is of note the case of ITGA7, which showed strong overexpression in FP + tumours." (PMID 36221013, 2022). "We matched the expression profiles of three prognostic genes in the TCGA-BLCA and GSE7476 datasets and found that both ITGA5 and ITGA7 were significantly reduced in tumor samples; while ITGB6 was notably overexpressed in the BLCA group (all P< 0.05)." (PMID 36267977, 2022). "ITGA7 expression was also tested for correlations with the standard prognostic factors tumour grade, lymph node status, and oestrogen-receptor status." (PMID 34253873, 2021). "Whereas, downregulated genes included GJA4, which is a component of gap junctions that are downregulated in CSCs, and BTNL9 and ITGA7, which are proposed tumour suppressors in breast." (PMID 34253873, 2021). "circ-ITGA7 hinders tumor progression in a dual way, in which the expression of its linear transcript is implicated." (PMID 34205978, 2021). "The top 10 downregulated genes are involved in different signalling pathways, such as the CHN2 gene in the regulation of RAC1 activity, the FOS gene in EGFR signalling and ITGA7 in integrin pathways and Akt signalling and in tumour initiation and progression." (PMID 32613561, 2020). "In conclusion, ITGA7 correlates with poor pathological differentiation, large tumor size, advanced TNM stage, and unfavorable survival profiles, and it promotes cell proliferation, stemness, but suppresses cell apoptosis in NSCLC." (PMID 31418948, 2019). "Further analysis illustrated that ITGA7 was upregulated in tumor tissues compared with the adjacent tissues in NSCLC patients (P < 0.001)." (PMID 31418948, 2019).
tumor (continued). "A total of 397 NSCLC patients underwent surgical resection were included, and ITGA7 was measured in tumor tissues and adjacent tissues by immunohistochemistry." (PMID 31418948, 2019). "There were 56.2% of patients whose tumor tissues presented ITGA7 high expression, and 43.8% of patients whose tumor tissues presented ITGA7 low expression." (PMID 31418948, 2019). "pAkt was suppressed in the drug-resistant tumor cell lines, particularly in A498 cells, following ITGA7 knock down, whereas pCdk1 and pCdk2 were elevated." (PMID 29721158, 2018). "Control studies demonstrated that specific ITGA7 down-regulation in the temsirolimus-sensitive as well as the temsirolimus-resistant tumor cells occurred." (PMID 29721158, 2018). "As few as 10,000 ITGA7+ cells were sufficient to generate visible tumours 4 months post injection, whereas, at least 100,000 ITGA7− cells were necessary to generate a tumour in the same mouse model." (PMID 27924820, 2016). "In the present study, we demonstrated that ITGA7+ cells were markedly enriched in residual OSCC xenograft tumours in NOD/SCID mice after treatment with cisplatin chemotherapy." (PMID 27924820, 2016). "In clinical OSCC specimens, ITGA7+ cells were expressed in <1% of tumour cells in most tumour tissues (203/262, 77.5%), which was consistent with CSC expectation." (PMID 27924820, 2016). "Others are more distinctive of a "state", e.g. distribution of cytokeratins and down-regulation of certain integrins (ITGA6/ITGB4, ITGA7) in all the tumour-derived cell lines." (PMID 16626496, 2006). "The expression levels of ITGA7 have been found to vary across different tumor types." (PMID 40076599, 2025). "Our analysis identified seven tumour suppressor genes (ITGA7, SLC45A1, TPPP, SCN4A, GIPR, SOGA3 and RAB6B) and six oncogenes (SAT1, SERPINE1, UPK2, SYT12, RASAL1 and CDH3) with significant false discovery rate (FDR)-adjusted P values (q-value) of less than 0.05." (PMID 38429478, 2024). "Although ITGA7 has been identified as highly expressed in OC compared to the normal ovarian surface epithelium and its overexpression indicates a poor prognosis, we revealed that ITGA7 functions as a tumor suppressor and restricts the malignant transition of ADSCs." (PMID 38233863, 2024). "In the present study, we measured the expression of tumor tissue ITGA7 in NSCLC patients and evaluated its correlation with patients' clinicopathological characteristics and survival profiles, as well as its influence on NSCLC cell proliferation, apoptosis, and stemness." (PMID 31418948, 2019). "However, patients with ITGA7 high expression presented larger tumor size, poorer pathological differentiation, and more advanced TNM stage compared with patients with ITGA7 low expression (all P < 0.05)." (PMID 31418948, 2019). "Examples about the expression of ITGA7 in tumor tissues and adjacent tissues were shown." (PMID 31418948, 2019). "Novel data point to the integrin subtype α7 (ITGA7) as a potential tumor biomarker and it has been speculated that ITGA7 could serve as a highly specific diagnostic and therapeutic target." (PMID 29721158, 2018). "Since integrin α7 (ITGA7) is speculated to promote metastasis, this investigation was designed to investigate whether temsirolimus-resistance is associated with altered ITGA7 expression in RCC cell lines and modified tumor cell adhesion and invasion." (PMID 29721158, 2018). "Whatever the exact mechanism, the results presented here indicate considerable ITGA7 traffic from inside the RCC cell to the outer membrane, which not only elevates tumor cell–matrix-interaction but also causes temsirolimus-resistant cells to become highly motile upon reexposure to temsirolimus." (PMID 29721158, 2018). "Cytoplasmic ITGA7 content was diminished in resistant compared to sensitive tumor cells." (PMID 29721158, 2018). "Therefore, regulation of tumor cell invasiveness cannot exclusively be ascribed to ITGA7, but involves other integrins." (PMID 29721158, 2018).